GPX8 (glutathione peroxidase 8 (putative))
Diseases named in the same sentence as GPX8 in open-access papers (continued):
Sharing a sentence is not in itself a finding about the gene and the disease.
colitis (6 papers, 2020 to 2025). Inflammation of the colon. "GPX8-deficient macrophages show a significant increase in IL-1β production under LPS stimulation, and C57BL/6 mice that received transplants of GPX8-deficient macrophages displayed a phenotype indicative of exacerbated colitis." (PMID 40273141, 2025). "It was shown that GPX8-deficient mice were more susceptible to colitis, and exhibited increased caspase-4/11 activation, with higher levels of caspase-induced inflammation during colitis and septic shock." (PMID 40563487, 2025). "For example, covalent binding between GPX8 and caspase 4 inhibited inflammation associated with colitis, and GPX8 was involved in protection from bleomycin-induced lung injury in IGF1R knockout animals." (PMID 36750850, 2023). "Inhibition of caspase‐4/11 activation with either N‐acetylcysteine, a strong antioxidant, or VX‐765, a caspase‐4 inhibitor, reduces colitis in Gpx8‐deficient mice." (PMID 31782617, 2020). "GPx8 binds covalently to caspase‐4/11 via disulfide bonding between cysteine 79 of GPx8 and cysteine 118 of caspase‐4 and thus restrains caspase‐4/11 activation, while GPx8 deficiency leads to caspase‐4/11‐induced inflammation during colitis and septic shock." (PMID 31782617, 2020). "Inhibition of caspase‐4/11 activation with small molecules reduces the severity of colitis in GPx8‐deficient mice." (PMID 31782617, 2020). "Treatment with NAC, a potent antioxidant, or with VX‐765, a caspase‐4 inhibitor, consistently suppressed caspase 4/11‐dependent inflammasome activation and reduced colitis severity in Gpx8‐deficient mice." (PMID 31782617, 2020). "Here, we show that mice lacking the oxidative stress sensor glutathione peroxidase 8 (GPx8) are more susceptible to colitis and endotoxic shock, and exhibit reduced richness and diversity of the gut microbiome." (PMID 31782617, 2020). "C57BL/6 mice that underwent adoptive cell transfer of GPx8‐deficient macrophages displayed a similar phenotype of enhanced colitis, indicating a critical role of GPx8 in macrophages." (PMID 31782617, 2020). "In this communication, we found that GPx8−/− mice exhibited exacerbated colitis induced by DSS and were more susceptible to endotoxic shock when challenged by LPS." (PMID 31782617, 2020). "Next, we tested whether GPx8 deficiency enhances the activation of the non‐canonical pathway in our colitis model by analyzing the colons for protein expression profiles in this pathway." (PMID 31782617, 2020). "To test whether macrophages deficient with GPx8 play a key role in the colitis phenotype, we examined Gpx8 expression profiles in both murine and human colon tissues by IHC analysis." (PMID 31782617, 2020). "Since the activation of caspase‐4/11 eventually leads to IL‐1β production, which plays a pivotal role in regulating innate‐immune responses and the homeostasis of colon epithelial cells, GPx8 deficiency may cause increased inflammation and high susceptibility to colitis." (PMID 31782617, 2020). "To further determine whether GPx8‐deficient macrophages contribute to the colitis phenotype, we performed an adoptive cell transfer experiment to examine the effect of GPx8‐deficient macrophages on disease progression under the same gut microbiota to avoid potential interference." (PMID 31782617, 2020). "Macrophages with a GPx8 deficit contribute to the dextran-sulfate-sodium (DSS)-induced colitis phenotype." (PMID 35208621, 2022). "Upregulation of proinflammatory cytokines and aggravation of colitis symptoms in Gpx8−/− mice was found to be dependent on its action on caspase-11." (PMID 35712726, 2022). "In conclusion, these results suggest that GPx8 protects against colitis by negatively regulating caspase‐4/11 activity." (PMID 31782617, 2020). "Full‐length caspase‐11 and caspase‐1, as well as processed caspase‐11 (p26), caspase‐1 (p20), and GSDMD (p30, a marker of cell pyroptosis), were elevated on day 7 in colon tissue of GPx8−/− mice with colitis compared with samples from WT mice." (PMID 31782617, 2020).
colitis (continued). "This study highlights how GPx8, an oxidative stress sensor, protects against colitis by negatively regulating caspase‐4/11 activity." (PMID 31782617, 2020). "In this study, we found that GPx8 in macrophages protected against DSS‐induced colitis and LPS‐induced sepsis and shaped the gut microbiome." (PMID 31782617, 2020). "GPX8 has been the least-characterized GPX, though several reports have implicated it in diverse cellular processes such as calcium homeostasis in ER, microsomal lipid composition regulation, and protection against chemical-induced colitis." (PMID 36750850, 2023). "In this case, one could argue that GPx8 acts as a negative regulator; it down-regulates caspase-4 activation and prevents colitis by decreasing caspase-4/11." (PMID 35208621, 2022). "Gpx8 knockout in mice severely exacerbated DSS-colitis and reduced gut microbiome diversity." (PMID 35712726, 2022). "In this study, we show that mice lacking the oxidative stress sensor GPx8 are more susceptible to colitis and endotoxic shock, and exhibit reduced richness and diversity of the gut microbiome." (PMID 31782617, 2020). "Age‐, sex‐, and weight‐matched WT and GPx8−/− mice were co‐housed for 3 weeks, then administered 4% DSS in their drinking water for 6 days to induce colitis; mortality rates were recorded." (PMID 31782617, 2020). "Mice transplanted with GPx8−/− macrophages displayed greater disease severity, and higher numbers of activated macrophages and increased cytokine production with DSS‐induced colitis compared with mice transplanted with GPx8+/+ macrophages." (PMID 31782617, 2020). "We therefore treated GPx8−/− mice with VX‐765, a caspase‐1/4 inhibitor, or N‐acetylcysteine (NAC), an ROS scavenger, to confirm the importance of the ROS‐modulating gene in the inflammasome pathway and colitis." (PMID 31782617, 2020). "Similarly, NAC treatment suppressed caspase‐4/11‐dependent inflammasome activation in GPx8−/− BMDMs (Fig EV4A) and reduced colitis severity in Gpx8−/− mice (Fig EV4B–E)." (PMID 31782617, 2020).
glioblastoma (5 papers, 2022 to 2024). The most malignant astrocytic tumor (WHO grade IV). "Downregulation of GPX8 has been found to suppress the migratory and invasive properties of glioblastoma cells." (PMID 38656879, 2024). "GPX8 was a valuable diagnostic biomarker in multiple cancers, including GBM/LGG (glioblastoma multiforme/Brain lower grade glioma), KIRC (kidney renal clear cell carcinoma), KIRP (kidney renal papillary cell carcinoma) and STAD (stomach adenocarcinoma)." (PMID 35402257, 2022). "The purpose of this study was to explore the expression and functions of GPX8 in glioblastoma (GBM)." (PMID 36061208, 2022). "GPX8 has not been extensively studied in the context of glioblastoma, and its specific role in this type of cancer is not well understood." (PMID 37795080, 2023). "DUSP26 is negatively correlated with GPX8, and low DUSP26 expression could lead to malignant behavior in glioblastoma cells by deregulating MAPK and Akt signaling pathway." (PMID 36052280, 2022).
lung cancer (5 papers, 2022 to 2024). A malignant neoplasm involving the lung. "Notably, in a recent study on lung cancer, researchers discovered that GPX8 expression on cancer-associated fibroblasts can promote the metastasis of lung cancer cells." (PMID 38515109, 2024). "The GPX8 expression level was positively associated with CAF infiltration in lung cancer." (PMID 35978854, 2022). "High expression of GPX8 was associated with CAF infiltration in lung cancer." (PMID 35978854, 2022). "Our finding indicated that GPX8 was highly expressed in CAF and closely associated with CAF infiltration in lung cancer." (PMID 35978854, 2022). "Bromodomain extra‐terminal inhibitor JQ1 downregulated GPX8 expression and suppressed lung cancer cell migration." (PMID 35978854, 2022). "In this study, pharmacologic inhibition and genetic silence of BRD2/BRD4 obviously downregulated GPX8 expression and prevented migration both in lung cancer cells and CAF." (PMID 35978854, 2022). "In this study, we identified GPX8 as a potential pro‐metastatic factor in lung cancer by in vitro and in vivo assays, which provides a new insight into the pathogenesis of lung cancer metastasis." (PMID 35978854, 2022). "BET inhibitors are promising epigenetic drugs under clinical estimation in various cancers, including lung cancer, which serves as an alternative strategy against GPX8‐facilitated metastasis." (PMID 35978854, 2022). "Our findings indicate that highly expressed GPX8 in lung cancer cells and fibroblasts functions as a pro‐metastatic factor in lung cancer." (PMID 35978854, 2022). "In the current study, GPX8 was identified as novel pro‐metastatic factor in lung cancer based on datasets analysis and experimental investigation." (PMID 35978854, 2022). "GPX8, which shows pro‐metastatic role both in cancer cells and CAFs, is a distinguishably promising target for lung cancer metastasis, so it is meaningful to explore potential strategies against GPX8‐mediated metastasis." (PMID 35978854, 2022). "GPX8 could impact the prognosis and tumorigenesis of nonsmall cell lung cancer patients via the regulation of epithelial characteristics." (PMID 37689745, 2023). "Thus, downregulation of GPX8 is a better approach to suppress its pro‐metastatic function in lung cancer." (PMID 35978854, 2022). "Moreover, the GEO datasets, including GSE4412-GPL97, GSE4271-GPL97, GSE17536 and GSE31210, showed that high GPX8 expression was correlated with poorer prognosis of patients with Brain cancer, Colorectal cancer and Lung cancer." (PMID 35402257, 2022). "JQ1 is identified as a potential inhibitor against GPX8‐mediated lung cancer metastasis." (PMID 35978854, 2022). "As expected, the BET inhibitor JQ1 could downregulate GPX8 expression in lung cancer A549 and NCI‐H1975 cells, and lung fibroblast MRC5 cells both in the protein level and mRNA level." (PMID 35978854, 2022). "Furthermore, GPX8 was overexpressed in cancer‐associated fibroblast (CAF) and associated with CAF infiltration in tumor microenvironment of lung cancer." (PMID 35978854, 2022). "GPX8 silence on fibroblasts suppressed lung cancer cell migration in the coculture system." (PMID 35978854, 2022). "Thus, BRD2 and BRD4 could regulate GPX8 expression and BET inhibitors may serve as a treatment strategy for GPX8‐driven lung cancer metastasis." (PMID 35978854, 2022). "BET proteins are involved in transcriptional regulation of GPX8 and BET inhibitor is a potential strategy against GPX8‐mediated lung cancer metastasis." (PMID 35978854, 2022). "In summary, GPX8 serves as a pro‐metastatic factor both in tumors and TME, which is a potentially therapeutic target in lung cancer." (PMID 35978854, 2022). "As BRD2 and BRD4 were validated as the upstream regulators of GPX8, inhibition of GPX8 by bromodomain and extra‐terminal (BET) inhibitors may serve as a novel therapeutic potential for lung cancer metastasis." (PMID 35978854, 2022).
lung cancer (continued). "Furthermore, the result showed that the expression level of GPX8 was positively correlated with IL6 and CCL2 in lung cancer." (PMID 35978854, 2022). "Knockdown of GPX8 obviously inhibited LUAD metastasis through the modulation of focal adhesion pathway and GPX8‐mediated IL6 and CCL2 production of CAF may play crucial role for lung cancer metastasis." (PMID 35978854, 2022). "The expression level of GPX8 was positively correlated with CCL2 and IL6 in lung cancer." (PMID 35978854, 2022). "Thus, GPX8‐mediated secretion of IL6 and CCL2 by CAF in TME may promote lung cancer metastasis." (PMID 35978854, 2022).
colorectal cancer (3 papers, 2022 to 2025). A primary or metastatic malignant neoplasm that affects the colon or rectum. "Materials and Methods: The expression of GPx4 and GPx8 in 58 specimens of human colorectal cancer tissues and normal tissues was detected by the indirect immunohistochemical method under a light microscope." (PMID 35208621, 2022). "Insufficient research on the relationship between GPx8 and human colorectal carcinoma prompted us to start an investigation into this area." (PMID 35208621, 2022). "In our study, the presence of GPx4 and GPx8 in healthy colons and colorectal carcinoma was estimated." (PMID 35208621, 2022). "However, to our knowledge, this is one of the first studies analyzing GPx8 presence in human colorectal carcinoma." (PMID 35208621, 2022).
lung adenocarcinoma (3 papers, 2022 to 2025). A carcinoma that arises from the lung and is characterized by the presence of malignant glandular epithelial cells. "Even after adjusting for confounding factors, GPX8 remained an independent prognostic predictor in lung adenocarcinoma patients." (PMID 38515109, 2024). "This compound has the potential to be used as a therapeutic drug targeting GPX8 for the treatment of lung adenocarcinoma." (PMID 38515109, 2024).
stomach adenocarcinoma (3 papers, 2022 to 2025). "We used the TIMER database to discover the association of GPX8 and tumor-infiltrating lymphocytes in stomach adenocarcinoma." (PMID 35712475, 2022). "Then, we discovered the association between GPX8 and prognosis of stomach adenocarcinoma with the GEPIA and Kaplan–Meier plotter databases." (PMID 35712475, 2022). "The GEPIA and Kaplan–Meier plotter databases showed that a higher GPX8 expression level was correlated with poor prognosis of stomach adenocarcinoma, suggesting that GPX8 was a risk factor of poor prognosis in stomach adenocarcinoma." (PMID 35712475, 2022). "The study employed a multi-omics approach to analyze GPX8 expression in both tumor and adjacent normal tissue of stomach adenocarcinoma (STAD), colon adenocarcinoma (COAD) and rectum adenocarcinoma patients." (PMID 39833079, 2025). "At last, Gene Ontology (GO) and Kyoto Encyclopedia of Genes and Genomes (KEGG) pathway analyses were used to demonstrate the biological functions of GPX8 in stomach adenocarcinoma." (PMID 35712475, 2022). "Secondly, the GEPIA and Kaplan–Meier plotter databases were conducted to discover the prognostic role of GPX8 in stomach adenocarcinoma." (PMID 35712475, 2022). "Combining the results of the GEPIA and TCGA databases, the GPX8 expression in stomach adenocarcinoma was higher than that in normal tissue." (PMID 35712475, 2022). "The Gene Expression Profiling Interactive Analysis (GEPIA) database and Kaplan–Meier plotter database were used to evaluate the prognostic survival of GPX8 in stomach adenocarcinoma." (PMID 35712475, 2022). "The mRNA expression of GPX8 in ArrayExpress was significantly higher in stomach adenocarcinoma than the adjacent normal tissue." (PMID 35712475, 2022). "Gene Set Enrichment Analysis (GSEA) was performed to reveal the biological functions including immune cells and signaling pathways of GPX8 in stomach adenocarcinoma." (PMID 35712475, 2022). "In this study, we comprehensively analyzed the expression of GPX8 in stomach adenocarcinoma and discovered that it is a potential target in the treatment of stomach adenocarcinoma." (PMID 35712475, 2022). "This study found that a high expression of GPX8 in stomach adenocarcinoma was correlated with poor prognosis." (PMID 35712475, 2022). "We investigated the expression of GPX8 between stomach adenocarcinoma and normal adjacent tissue with the GEPIA database." (PMID 35712475, 2022). "We conducted Gene Ontology (GO) analysis and Kyoto Encyclopedia of Genes and Genomes (KEGG) analysis to explore the biological signatures of GPX8 in stomach adenocarcinoma." (PMID 35712475, 2022). "Firstly, the Gene Expression Profiling Interactive Analysis (GEPIA) and The Cancer Genome Atlas (TCGA) datasets were used to analyze the expression of GPX8 in stomach adenocarcinoma and adjacent normal tissues." (PMID 35712475, 2022). "TCGA database also indicated that GPX8 was significantly higher in stomach adenocarcinoma than the adjacent normal tissue." (PMID 35712475, 2022). "Specifically, we discovered the mRNA expression of GPX8 in stomach adenocarcinoma and normal adjacent tissue with the GEPIA database and TCGA database." (PMID 35712475, 2022). "Based on the GEPIA and TCGA databases, the mRNA expression of GPX8 was significantly higher in stomach adenocarcinoma compared with the adjacent normal tissues." (PMID 35712475, 2022). "After analyzing the mRNA expression and prognosis survival of GPX8 in stomach adenocarcinoma, we intended to investigate the correlation between the GPX8 expression level and immune status in the tumor microenvironment of stomach adenocarcinoma." (PMID 35712475, 2022). "The GEPIA database showed that GPX8 was significantly higher in stomach adenocarcinoma than the adjacent normal tissues." (PMID 35712475, 2022). "In addition, we also used the GSEA database to investigate the correlation between GPX8 and immune cells’ status in the tumor microenvironment of stomach adenocarcinoma." (PMID 35712475, 2022).
stomach adenocarcinoma (continued). "In addition, the result of the GEPIA database indicated that the mRNA expression of GPX8 in stomach adenocarcinoma was significantly higher than the adjacent normal tissue (P<0.05)." (PMID 35712475, 2022). "A higher GPX8 expression level was correlated with poor survival of stomach adenocarcinoma." (PMID 35712475, 2022). "In this study, we aim to discover the correlation between GPX8 and stomach adenocarcinoma." (PMID 35712475, 2022). "Additionally, we conducted GO, KEGG, and GSEA databases to analyze the biological signatures of GPX8 in stomach adenocarcinoma." (PMID 35712475, 2022). "We hope to identify the function of GPX8 in stomach adenocarcinoma with this research." (PMID 35712475, 2022). "GPX8 is an important factor which might be a potential target in the treatment of stomach adenocarcinoma." (PMID 35712475, 2022). "Therefore, GPX8 might exacerbate the stomach adenocarcinoma by enhancing the inflammation of tumor microenvironment." (PMID 35712475, 2022). "Therefore, GPX8 might increase carcinogenesis of stomach adenocarcinoma by modulating collagen fibril and the extracellular matrix." (PMID 35712475, 2022). "Thus, we aimed to discover the function of GPX8 in stomach adenocarcinoma in this study." (PMID 35712475, 2022). "The TIMER database showed that the GPX8 expression level was positively correlated with infiltrating levels of CD8+ T cells, CD4+ T cells, macrophages, neutrophils, and dendritic cells in stomach adenocarcinoma." (PMID 35712475, 2022). "The function of GPX8 in stomach adenocarcinoma has not been discovered clearly." (PMID 35712475, 2022).
brain cancer (2 papers, 2022). A primary or metastatic malignant neoplasm affecting the brain. "The analysis revealed that GPX8 was upregulated in breast, cholangio, colorectal, esophagus, kidney, liver, lung, stomach, and brain cancers compared with homologous normal tissues." (PMID 36061208, 2022).
clear cell renal cell carcinoma (2 papers, 2023 to 2024). "In clear cell renal cell carcinoma, GPX8 regulates NNMT expression through the IL6-STAT3 signaling axis and inhibits ccRCC cell survival by blocking this axis through activation of AMPK." (PMID 38515109, 2024). "In clear cell renal cell carcinoma, GPX8 silencing inhibits tumorigenesis by regulating nicotinamide N-methyltransferase (NNMT)." (PMID 38515109, 2024).